RNU6-139P (RNA, U6 small nuclear 139, pseudogene)
Gene: Small nuclear RNA gene on chromosome 3 (62,814,382 to 62,814,491, forward strand). Ensembl gene ENSG00000252449.
Homologues: Orthologues: chimpanzee U6 (99% identical), macaque U6 (82% identical), pig U6 (65% identical). Paralogues in human: RNU6-11P (84% identical), RNU6-37P (84% identical), RNU6-25P (83% identical), RNU6-29P (83% identical), RNU6-1 (82% identical), RNU6-12P (82% identical), RNU6-13P (82% identical), RNU6-175P (82% identical), RNU6-17P (82% identical), RNU6-18P (82% identical), RNU6-2 (82% identical), RNU6-32P (82% identical), and 1287 more.